TSLIG2 (tRNA splicing ligase complex subunit 2)
Description:
Accessory subunit of the tRNA-splicing ligase complex that acts by directly joining spliced tRNA halves to mature-sized tRNAs by incorporating the precursor-derived splice junction phosphate into the mature tRNA as a canonical 3',5'-phosphodiester. May act as an RNA ligase with broad substrate specificity and may function toward other RNAs.
Synonyms: C2orf49; ASW; MGC5509
Tractability: PROTAC: its protein half-life has been measured.
Gene: Protein-coding gene on chromosome 2 (105,337,532 to 105,350,712, forward strand). Ensembl gene ENSG00000135974.
Subcellular location: Nucleus
Subcellular location (Human Protein Atlas): Nucleoplasm
Pathways (Reactome):
Metabolism of RNA: tRNA processing in the nucleus
Gene Ontology:
Molecular function: protein binding
Biological process: tRNA splicing, via endonucleolytic cleavage and ligation; embryonic morphogenesis
Cellular component: nucleoplasm; nucleus; tRNA-splicing ligase complex; cytoplasm
Genetic constraint (gnomAD): Loss-of-function variants: 11 observed, 20.79 expected, observed/expected ratio (o/e) 0.53, 90% interval 0.33 to 0.88. The upper end of that interval is the gene's LOEUF score, 0.88, which puts it in group 3 of 6, group 1 being the genes least tolerant of losing a copy. Missense variants: 288 observed, 285.67 expected, observed/expected ratio (o/e) 1.01, 90% interval 0.92 to 1.11. Synonymous variants: 134 observed, 113.27 expected, observed/expected ratio (o/e) 1.18, 90% interval 1.03 to 1.37.
Homologues: Orthologues: chimpanzee C2AH2orf49 (99% identical), macaque C13H2orf49 (99% identical), dog C2orf49 (92% identical), rabbit C2orf49 (91% identical), pig C2orf49 (91% identical), rat C9h2orf49 (86% identical), mouse AI597479 (85% identical), guinea pig C2orf49 (81% identical), tropical clawed frog c2h2orf49 (46% identical), zebrafish C9H2orf49 (42% identical).